TRIM54 (tripartite motif containing 54)
Description:
May bind and stabilize microtubules during myotubes formation.
Synonyms: MuRF; MuRF-3; MuRF3; RNF30
Tractability: Antibody: the Human Protein Atlas places it where antibodies can reach.
Gene: Protein-coding gene on chromosome 2 (27,282,366 to 27,309,400, forward strand). Ensembl gene ENSG00000138100.
Subcellular location: Cytoplasm, cytoskeleton; Cytoplasm, myofibril, sarcomere, Z line
Subcellular location (Human Protein Atlas): Cytosol; Plasma membrane
Gene Ontology:
Molecular function: protein binding; ubiquitin protein ligase activity; zinc ion binding; microtubule binding
Biological process: innate immune response; microtubule-based process; negative regulation of microtubule depolymerization; signal transduction
Cellular component: cytoplasm; microtubule; cytoskeleton; microtubule associated complex; Z disc
Genetic constraint (gnomAD): Loss-of-function variants: 40 observed, 42 expected, observed/expected ratio (o/e) 0.95, 90% interval 0.74 to 1.24. The upper end of that interval is the gene's LOEUF score, 1.24, which puts it in group 5 of 6, group 1 being the genes least tolerant of losing a copy. Missense variants: 485 observed, 490.46 expected, observed/expected ratio (o/e) 0.99, 90% interval 0.92 to 1.07. Synonymous variants: 199 observed, 201.14 expected, observed/expected ratio (o/e) 0.99, 90% interval 0.88 to 1.11.
Homologues: Orthologues: chimpanzee TRIM54 (100% identical), macaque TRIM54 (99% identical), dog TRIM54 (98% identical), guinea pig TRIM54 (97% identical), rat Trim54 (96% identical), mouse Trim54 (95% identical), tropical clawed frog TRIM54 (80% identical), zebrafish trim54 (66% identical). Paralogues in human: TRIM55 (62% identical), TRIM63 (57% identical), MID1 (22% identical), TRIM36 (22% identical), MID2 (21% identical), TRIM46 (21% identical), TRIM67 (20% identical), TRIM9 (20% identical), TRIM71 (18% identical), TRIM47 (18% identical), TRIM7 (18% identical), TRIM11 (17% identical), and 68 more.
Diseases named in the same sentence as TRIM54 in open-access papers:
TRIM54 is named in the same sentence as 33 diseases in open-access papers, as found by Europe PMC text mining. Sharing a sentence is not in itself a finding about the gene and the disease. The quoted sentences say what the papers report.
hepatocellular carcinoma (5 papers, 2021 to 2025). A malignant tumor that arises from hepatocytes. "Sorafenib induces ferroptosis in hepatocellular carcinoma by promoting TRIM54-mediated ubiquitination and degradation of FSP1 via the ERK pathway, with FSP1 reducing sorafenib sensitivity and enhancing tumor development." (PMID 39315094, 2024). "In hepatocellular carcinoma cells, TRIM54 overexpression results in the significant activation of the Wnt/b-catenin pathway." (PMID 37511041, 2023). "Importantly, statistical analysis showed that hepatocellular carcinoma patients with a high TRIM54 expression had a significantly worse overall survival and higher recurrent rate than those with a low TRIM54 expression." (PMID 34956880, 2021). "The increased expression of TRIM54 was detected in the clinical hepatocellular carcinoma tissue samples, but not detectable in adjacent normal liver tissue from the same HCC patient." (PMID 34956880, 2021). "For hepatocellular carcinoma (HCC), we performed a tumor classification using a 4-gene signature (CYP26B1, MCM10, SPINK4, and TRIM54) derived from differentially expressed genes (DEGs) associated with ubiquitination." (PMID 38870259, 2024).
acute myocardial infarction (4 papers, 2015 to 2021). Necrosis of the myocardium, as a result of interruption of the blood supply to the area. "For example, the germ line deletion of Trim54/MuRF3 predisposed the heart for failure and rupture during acute myocardial infarction in mice." (PMID 34572540, 2021). "It is also reported that TRIM54 was a novel and sensitive biomarker for the diagnosis of acute myocardial infarction, and heterozygous TRIM54 mutation may contribute to cardiac and skeletal protein aggregate myopathy." (PMID 34956880, 2021). "Trim54 is essential for maintenance of ventricular integrity and function after myocardial infarction." (PMID 25599194, 2015).
hypertrophic cardiomyopathy (4 papers, 2015 to 2021). A condition in which the myocardium is hypertrophied without an obvious cause. "In addition, it has been shown that a homozygous TRIM63/MuRF1 null mutation in combination with the heterozygous TRIM54/MuRF3 mutation leads to a myosin storage myopathy associated with skeletal muscle hypertrophy and hypertrophic cardiomyopathy in patients." (PMID 34572540, 2021).
gastric cancer (3 papers, 2024 to 2025). A primary or metastatic malignant neoplasm involving the stomach. "FLNC suppresses gastric cancer progression by stabilizing TRIM54 and is linked to cytoskeletal remodeling, a process modulated by FAT1 in EMT." (PMID 40672387, 2025). "A significantly upregulated level of TRIM54 was observed in human gastric cancer tissues, which was closely associated with advanced tumor stages, increased metastasis, and poorer overall survival." (PMID 39768197, 2024). "This interaction suggested a regulatory mechanism where TRIM54 overexpression exerted a positive influence on gastric cancer aggressiveness." (PMID 39768197, 2024). "TRIM54 was highly expressed in gastric cancer cells and tissues, and high expression of TRIM54 was correlated to decreased survival rate of patients with gastric cancer." (PMID 38870259, 2024). "Overexpression of TRIM54 can facilitate cancer progression by promoting cell proliferation, invasion, and migration in AGS and HGC27 cells, and its knockdown suppressed gastric cancer progression in vivo in a xenograft model." (PMID 39768197, 2024).
cardiomyopathy (2 papers, 2015 to 2020). A disease of the heart muscle or myocardium proper. "The development of cardiomyopathy and skeletal myopathy associated with subsarcolemmal myosin accumulation and non-ubiquinated aggregates of fragmented sarcomeres were observed in a patient with compound MuRF1 (TRIM63) deficiency and a deleterious MuRF3 (TRIM54) missense mutation." (PMID 33234710, 2020).
infectious mononucleosis (1 paper, 2026). A condition characterized by an increase in mononuclear white blood cells and swollen lymph nodes, which is usually caused by infection with the Epstein-Barr virus. "Clinically, elevated TRIM54 expression is detected in circulating monocytes from pediatric patients with Epstein-Barr virus-induced infectious mononucleosis." (PMID 42212562, 2026).
liver cancer (1 paper, 2022). An epithelial or non-epithelial malignant neoplasm that arises from the liver. "Overall, S100A9, SLC22A15, TRIM54, and PPARGC1A were screened as TIMGs that can be used for prognostic prediction and be the potential targets of the ICI treatments for patients with liver cancer." (PMID 36120553, 2022). "In our results, S100A9, SLC22A15, TRIM54, and PPARGC1A were identified as TIMGs, which were identified as prognostic biomarkers for liver cancer sufferers." (PMID 36120553, 2022). "Finally, the mechanism of TRIM54 and SLC22A15 affecting liver cancer development through TAMs is still unclear, and further research was warranted." (PMID 36120553, 2022).
pancreatic cancer (1 paper, 2024). "The major molecular subtypes of pancreatic cancer, classical and basal-like (or quasi-mesenchymal), are represented in this single-cell transcriptome landscape as Ep_TRIM54 and Ep_KRT6A, respectively." (PMID 38297291, 2024). "Notably, we found that Ep_VGLL1 was spatially correlated with both Ep_TRIM54 and Ep_KRT6A whereas these two major populations representing classical and basal-like subtypes of pancreatic cancer, respectively, were not directly adjacent to each other." (PMID 38297291, 2024).
tendinopathy (1 paper, 2023). "In this study, we initially observed that TRIM54 levels are significantly decreased in human tendinopathy samples compared to normal tendons." (PMID 38042492, 2023). "Consequently, this study contributes to the comprehension of TRIM54's role in tendinopathy and identifies a novel treatment axis for tendon injury." (PMID 38042492, 2023). "However, targeting candidates, such as TRIM54, could provide valuable alternative treatment options for treatment of tendinopathy." (PMID 38042492, 2023).
tendonitis (1 paper, 2023). "To further elucidate its role on tendonitis, we overexpressed TRIM54 in TDSCs and confirmed its levels using qRT-PCR." (PMID 38042492, 2023). "This study is to understand the role of TRIM54 (tripartite motif containing 54) in tendonitis through in vitro modeling with tendon-derived stem cells (TDSCs) and in vivo using rat tendon injury model." (PMID 38042492, 2023). "Additionally, we confirmed that TRIM54 significantly reverses inflammation and injury using in vivo tendonitis models." (PMID 38042492, 2023).
cancer (9 papers, 2019 to 2024). A tumor composed of atypical neoplastic, often pleomorphic cells that invade other tissues. "Most importantly, we discovered that Ep_VGLL1 was spatially correlated with both classical (Ep_TRIM54) and basal-like cancer (Ep_KRT6A) clusters." (PMID 38297291, 2024). "Concurrently, the protein level of S100A9, SLC22A15, and TRIM54 was found to be much higher in the cancer tissues or the cells around the blood sinus compared to the normal tissues." (PMID 36120553, 2022). "Further analysis suggested that modulation of angiogenesis-related genes (including ANGPTL4, FN1, HSPG2, SRPX2, KLK5, L1CAM, Prr22, FOXJ1, IL24, and TRIM54) potentially contributes to anlotinib resistance, as anlotinib is a multi-targeted anti-angiogenesis drug for cancer therapy." (PMID 31572680, 2019). "It has been shown in previous studies that the E3 ubiquitin ligases, such as RNF146, TRIM11, TRIM32, TRIM54, TRIM65 and UBE3C promote various cancers by triggering Wnt/β-catenin signaling via degradation of Axin1." (PMID 37379772, 2023). "The previous studies using PLATO have identified a set of TRIM proteins (TRIM1/MID2, TRIM18/MID1, TRIM54 and TRIM55) as cancer autoantigens of paraneoplastic neurological disorder (PND)." (PMID 31494268, 2019). "Intriguingly, we found that none of the major cancer cell subclusters (Ep_TRIM54, Ep_VGLL1, and Ep_KRT6A) exhibited preferences for Fb_LRRC15." (PMID 38297291, 2024). "Among the remaining 8 DEGs (ADRA2A, P2RX6, XCL2, XCL1, CCL7, TRIM54, TNFRSF18 and SPOCK1), the expression of ADRA2A, the top one, in KIRC based on individual cancer is lower than the normal tissues, but patients with lower expressed ADRA2A have a better overall survival (OS)." (PMID 31159832, 2019).
tumor (5 papers, 2021 to 2025). "Immunohistochemistry analysis showed that CYP26B1, MCM10, SPINK4, and TRIM54 were highly expressed in tumor tissue compared to normal tissue." (PMID 38870259, 2024). "A subcutaneous xenografted tumor model was firstly used to examine the biological function of TRIM54 in HCC progression in vivo." (PMID 34956880, 2021). "Collectively, these results demonstrate that TRIM54 functions as a tumor oncogenic gene in HCC in vivo." (PMID 34956880, 2021). "Tumor tissues exhibited high expression levels of CYP26B1, MCM10, SPINK4, and TRIM54 in the current study." (PMID 38870259, 2024). "Tumor tissues exhibited elevated expression levels of CYP26B1, MCM10, SPINK4, and TRIM54 compared to normal liver tissues, as indicated by the results." (PMID 38870259, 2024).
myopathy (4 papers, 2013 to 2021). A disease of the muscle in which the muscle fibers do not function properly. "Likewise, the combined germ line deletion of Trim63/MuRF1 and Trim54/MuRF3 as well as the deletion of Trim55/MuRF2 and Trim54/MuRF3 caused a myosin storage myopathy of the heart and skeletal muscle in mice." (PMID 34572540, 2021).
TRIM54 also shares sentences with these, for which no sentence is quoted: cardiac hypertrophy (5 papers); diabetes (2); diabetic cardiomyopathy (2); infection (2); muscle atrophy (2); myofibrillar myopathy (2); Myosin Storage Myopathies (2); Atrophy (1); chronic heart failure (1); dementia (1); distal myopathy (1); endometriosis (1); heart failure (1); Hyperglycemia (1); Insulin resistance (1); sarcopenia (1); Sepsis (1); Skeletal muscle hypertrophy (1); Skeletal myopathy (1); type 2 diabetes (1).